CD4 (CD4 molecule)
Diseases named in the same sentence as CD4 in open-access papers (continued):
Sharing a sentence is not in itself a finding about the gene and the disease.
lymphoma (continued). "In addition, MDV transforms CD4+ T cells into lymphoma cells, resulting in their proliferation and subsequent enlargement in the spleens of infected chickens." (PMID 41013577, 2025). "In lymphoma patients, a weak correlation was noted between the frequency of antigen-specific memory T cells and naïve T cells (CD4, r = 0.14, p = 0.38 (ns) and CD8, r = 0.31, p = 0.047) indicating that the abundance of naïve T cells is critical for mounting virus-specific responses." (PMID 40630518, 2025). "We aimed to use flow cytometry to analyze the proportions of PD-1-expressing CD4+, CD8+, and γδ T-cells in the spleen and tumor tissues of chickens that developed lymphomas to investigate the association between PD-1 expression and immunosuppression induced by MDV." (PMID 40430752, 2025). "In addition, MDV transforms CD4+ T cells into lymphoma cells, resulting in their proliferation and subsequent enlargement of the spleens in infected chickens." (PMID 40733525, 2025). "In addition to lytic replication, MDV establishes latent infection in CD4+ T cells, and only a few infected cells are subsequently transformed, resulting in the development of lymphomas in infected chickens." (PMID 40673706, 2025). "Furthermore, characterization of certain lymphomas, such as primary cutaneous CD4 + small/medium T-cell lymphoma (PC-CD4 + T-cell LPD), has highlighted their benign behavior, and has led to reclassification as lymphoproliferative disorder." (PMID 40616614, 2025). "To assess the cytotoxic potential of TFK cells, we performed a killing assay using FACS-sorted CD19+ B cells (predominantly malignant lymphoma cells) and co-cultured with either CD4+PD-1+CXCR5+TIA-1– TFH or CD4+PD-1+CXCR5+TIA-1+ TFK FACS-sorted from FL and DLBCL samples." (PMID 41030456, 2025). "Flow cytometry identified 37% aberrant large CD4+ T cells, suggesting lymphoma." (PMID 40874640, 2025). "Although FLCs show certain advantages as early risk warning biomarkers, discrepancies in predictive timing have been reported, which may be influenced by multiple factors, including CD4+ T-cell counts, viral load, and lymphoma subtypes." (PMID 40723865, 2025). "We next investigated whether EBV lymphoma cells can impair the immune function of PBMCs, including CD4+ T cells, through the upregulation of IRF4." (PMID 40733503, 2025). "HIV-induced decline in CD4+ T-cells weakens immune surveillance, increasing lymphoma risk, particularly in individuals not receiving cART." (PMID 41148820, 2025). "MDV can transform CD4+ T cells increasing their proliferation and the formation of lymphomas." (PMID 41013577, 2025). "Collectively, these findings suggest a differentiation trajectory from TFH to GZMK+ TFK to GZMB+ TFK and finally GZMB+CXCR5–CD4+ T-cell phenotypes during lymphoma progression, reflecting the convergence of cytotoxic CD4+ and CD8+ T cells into exhausted T cells." (PMID 41030456, 2025). "CD4 + T follicular helper cells (cTfh), which assist B cells within the germinal center, are essential for generating a strong antibody response, were reduced in lymphoma patients compared to HC." (PMID 40630518, 2025). "At diagnosis of lymphoma, 16 patients (59.2%) had CD4 counts <200 cells/mm3." (PMID 38406522, 2024). "Moreover, hAITL biopsies treated with the same drug significantly reduced the CD4 + PD-1high lymphoma cells." (PMID 38321568, 2024). "For this reason, we used here an mAITL preclinical mouse model for the generation of CAR T cells since they contain in the lymphoma microenvironment next to the malignant CD4 + T cells, all the key immune players such as B cells, CD8 T and myeloid cells such as follicular DCs." (PMID 39272178, 2024). "Spleen micronodules, visible only with the use of a high-frequency liner ultrasound probe, have been described in pathological conditions such as lymphoma, sarcoidosis, extrapulmonary tuberculosis, and low-CD4+ HIV, but also in healthy children and adolescents." (PMID 39178305, 2024).
lymphoma (continued). "Patients vaccinated between lymphoma treatment initiation and one year after its completion showed a poor antibody response but preserved CD4 and CD8 T cell responses, contrasting with a preserved B cell vaccinal response when vaccination was completed before the treatment initiation." (PMID 39902042, 2024). "Elevated levels of CD4+ PD-1+ lymphocytes were associated with substage B lymphoma but not with survival time." (PMID 38893123, 2024). "Rarely, prurigo nodularis may be the presenting symptom of a systemic disease such as HIV (CD4+ count less than 200), mycobacteria, a parasitic infection, or lymphoma." (PMID 39171012, 2024). "Finally, there was an equivalent increase in regulatory T cells (Tregs, CD4+FOXP3+) among mutant genotypes in the end-stage lymphomas, suggesting additional layers of immune dysfunction." (PMID 38570506, 2024). "It is unclear whether the reduction in IFN-γ+ and increase in IL-17A+ T cells at 21 dpi relate to CD4+ T cell expansion and aggravation of lymphoma." (PMID 37631976, 2023). "However, verification of clinical information revealed that three subjects developed lymphoma or used other adjuvant agents to improve CD4 count in follow-up." (PMID 37828979, 2023). "One phase I clinical trial (NCT03829540) uses CAR-T to target CD4 for T-cell leukemia/lymphoma." (PMID 37108359, 2023). "Notably, we observed that CD4+ T cells had closer proximity to lymphoma B cells than CD8+ T cells or other immune cells." (PMID 37591873, 2023). "The T-cell lymphomas were a mixture of DP, DN and SP (CD4+/CD8+) lymphomas." (PMID 37160922, 2023). "The median CD4+ T-cell count at lymphoma diagnosis was 15.50% (range: 2.00–36.00%; IQR: 15.00%)." (PMID 37190220, 2023). "Because co-culture with the anti-TCRVβ CAR-iNKT cells could block subsequent staining with the same anti-TCRVβ antibody clone, we used the immunophenotype CD4+CCR4med/hiCD26- to identify the lymphoma/leukaemia cells in PBMC from patients with ATL." (PMID 36936927, 2023). "Positive CD56 and EBER can also be found in ENK/T lymphoma, with positive CD4 or CD8 in some cases." (PMID 36135102, 2022). "Univariate analysis showed that the age, symptoms B, treatment status, IPI, pathological stage, ECOG PS, CD4+ cell count, β2 microglobulin, LDH, and CONUT score were factors influencing the prognosis of patients with HIV infection-associated lymphoma (p < 0.05)." (PMID 36438738, 2022). "Moreover, very little information is available on the expression and regulation of the selenoproteome in CD4 T cells, either originating from lymphoma or from healthy donors." (PMID 35163318, 2022). "Finally, when comparing these donor-derived CD4 T-cells with lymphoma-derived cell lines, common features emerged, most notably the high expression of GPX4, TXNRD1 and SELENOT transcripts." (PMID 35163318, 2022). "Furthermore, data show a majority of adult T cell leukaemia/lymphoma cells which share the Treg phenotype, CD4+CD25+CCR4+FOXP3+, leading to the suggestion that adult T cell leukaemia/lymphoma cells are descendants of Tregs." (PMID 36794233, 2022). "Moreover, it appeared that selenium-specific regulation of transcripts was more pronounced in primary CD4 T cells than in lymphoma-derived cell lines, although with a subtle donor-specific pattern." (PMID 35163318, 2022). "Previous studies indicated that early lymphomagenesis in lymphomas is a process related to CD4 + T cells stimulated by H. pylori antigens, and the proliferation of B-cell gastric lymphoma is dependent on CD40-mediated signaling, Th2 activities, co-stimulatory CD80, and CD86." (PMID 34980267, 2022). "Despite the STAT5B hyperactivation and the presence of multiple STAT5B mutations, the clinical course of CD4+ T-LGLL is indolent, and patients rarely have symptoms, differentiating it from CD8+ T-LGLL and other mature and immature CD4+ T-cell leukemias and lymphomas." (PMID 35210405, 2022).
lymphoma (continued). "CD4 is also expressed in Peripheral T-cell lymphomas (PTCLs) and CD4CAR NK-92 cells could also eliminated CD4+ T-cell leukemia and lymphoma cells in vitro and reduced tumor burden and prolonged survival in a T cell lymphoma xenograft model." (PMID 35493522, 2022). "A prior study of 39 older adults with EBV+ nodal cytotoxic TCL showed intermittent bone marrow invasion in 11 patients (29%), thrombocytopenia in 21 (62%), and hemophagocytosis in 13 (38%), and lymphoma cells had CD4+ (15%), CD8+ (64%), and CD56+ (15%) T/NK-cell phenotypes." (PMID 34088321, 2021). "We analyzed a variety of clinical factors (gender, age, risk stratification, clinical stage, CAR-T cell dose, serum peak concentration of IL-6 and CRP, CD4/CD8, etc.)that may be associated with CRS in patients with lymphoma, separately." (PMID 33708205, 2021). "Moreover, a large US study reported that Kaposi sarcoma and lymphoma rates were highest in the first six months of treatment particularly among individuals with low CD4 counts." (PMID 34886257, 2021). "Interestingly, inflamed cHLs harbor high numbers of PD-L1+ TAMs, that presumably represent an active immune evasive strategy elicited within the TME to suppress lymphoma-specific PD-1+ CD4+ T cells." (PMID 33842331, 2021). "Immune subsets of prognostic interest include, among others: CD68+ lymphoma-associated macrophages, CD3+ T cells, CD4+ T helper cells, CD8+ cytotoxic T cells, CD4+FOXP3+ T regulatory cells (Tregs), CD21+ dendritic cells, mast cells, and PD-1 expressing T-cells." (PMID 33929583, 2021). "Eleven patients (40.7%) (10 SS, 1 MF) had CD4+ lymphoma cells in the PB." (PMID 34335777, 2021). "CD4:CD8b ratio in unstimulated koala PBMCs was markedly higher in the KoRV-B-positive, KoRV-C-negative individual (KM, which showed lymphoma) than in koalas with endogenous infection only (KoRV-A); however, this ratio showed no other significant differences between KoRV subtype infection profiles." (PMID 33316950, 2020). "Together, these results presented evidence of impaired CD4+ and CD8+ T cell surveillance directed against EBV in HIV-positive individuals, with exacerbated immune defects observed in advanced HIV disease and HIV-positive patients with EBV-associated lymphoma." (PMID 33102204, 2020). "CD4+ T cells recognize, again, a wider spectrum of lytic antigens including late viral gene products, and such late lytic EBV antigen specific CD4+ T cells have been found to inhibit EBV associated lymphoma formation in mice." (PMID 32512847, 2020). "Furthermore, the degree of CD4 cell depletion has a major impact on the type of lymphoma that develops." (PMID 32803474, 2020). "Compared with CD4+ T cells of the control group, MDV mainly altered the ubiquitylome associated with the signal transduction, immune system, cancer, and infectious disease pathways in T lymphoma cells." (PMID 31035338, 2019). "In addition, TRAPs from the hepatic carcinoma Hepa1–6, lung cancer LLC or lymphoma EL4 cells also potently enhanced IL-6 secretion in CD4+ T cells." (PMID 31300052, 2019). "SPTCL is distinct from primary cutaneous γ/δ T-lymphomas, which are typically CD4-, CD8-, CD56+, granzyme B+, perforin+, TIA1+, may involve the epidermis and/or dermis, may present with panniculitic pattern and invariably have a very poor prognosis." (PMID 31311562, 2019). "As compared to primary CD4+ T cells, A3G is highly expressed in the HuT78 lymphoma cell line." (PMID 30791937, 2019). "Similarly, MDV can only be detected in less than 2% of MDV-transformed CD4+ T cell lines, and lipid metabolism is highly activated in lymphoma cells." (PMID 30971474, 2019).
lymphoma (continued). "In addition, PD-1 expression on peripheral CD4+ T cells obtained from dogs with lymphoma was significantly higher compared to that in control animals." (PMID 30040869, 2018). "Other specific feline antibodies (anti-CD4, anti-CD8α, anti-CD8β) can be used to detect additional epitopes and define the immunophenotype of lymphomas, but their routine clinical application is limited by the fact that formalin-fixed samples cannot be used as frozen sections are required." (PMID 30305106, 2018). "Malignant hematologic diseases may, in general, reduce lymphocyte counts in up to 60% of patients, and lymphoma in particular may affect an entire spectrum of lymphocyte subpopulations, including CD4+, CD8+, CD19+, and CD56+ cells." (PMID 30723478, 2018). "Interestingly, Eμ‐MYC/Vav‐BFL1 DT mice developed mainly immature (B220+ IgM−) lymphomas, with a significant proportion (64%) that additionally developed CD19−B220+CD4+ stem/progenitor cell lymphomas in the thymus." (PMID 29498802, 2018). "Another alteration observed was expansion, not higher than 20%, of some TCR-Vβ families in the EBV response in this group of patients; for instance, the frequency of Vβ5.3+ and Vβ4+ CD4+ T cells in one patient at stage 1 and in 1 patient with lymphoma, respectively." (PMID 30337929, 2018). "Interestingly, UBR5 RNA levels were decreased in all T-cell leukemia/lymphoma cell lines compared to naïve and memory CD4 T-cells, suggesting a post-transcriptional method of regulation." (PMID 29441057, 2018). "In addition, the expression of PD-1 on CD4+ lymphocytes obtained from PBMCs and LNCs was also significantly higher in the lymphoma group." (PMID 30040869, 2018). "Indeed, CD4CAR NK-92 cells specifically and effectively target CD4-expressing leukemia and lymphomas, as a proof of concept for allogeneic or autologous NK cell-based CAR therapy for CD4+ PTCLs." (PMID 29348865, 2017). "We found that CD4CAR NK-92 cells exhibit robust anti-tumor cytotoxicity ex vivo against both adult and pediatric CD4+ lymphoma/leukemia cell lines, CD4+ T-cells isolated from umbilical cord blood, as well as against untreatable primary CD4+ T-cell malignancies from adult and pediatric patients." (PMID 29348865, 2017). "Transformed CD4+ T cells (lymphoma) may express inhibitory markers, and suppress anti-tumour immunity." (PMID 29267390, 2017). "Likewise, these data demonstrate a dose-dependent response and profound CD4CAR NK-92 cell anti-tumor activity in a cell line and patient sample setting for both adult and pediatric CD4+ T cell leukemias and lymphomas." (PMID 29348865, 2017). "Median CD4+ T-lymphocyte count at lymphoma diagnosis was 188 cells/μL (range, 10 to 535 cells/μL)." (PMID 28717763, 2017). "MDV-induce lymphoma cells expressed significantly lower levels of TGF-beta receptors compared to the primary naïve CD4+ T cells isolated from line P birds, suggesting that these cells may be resistant to inhibitory effects of TGF-beta on proliferation." (PMID 29267390, 2017). "A minority (<10 %) of CD4 dim CD14 positive monocytes among the lymphoma cells was also documented." (PMID 27567676, 2016). "Similarly, in an isolated study evaluating the role of CD4 cytopenia and low CD4+/CD8+ ratio, these factors were the dominant predictors of lymphoma risk." (PMID 27429984, 2016). "Besides its direct effects on DC, expression of TIM-3 on lymphoma endothelial cells has been shown to suppress the activation of CD4+ T cells." (PMID 27973435, 2016). "In addition to direct apoptotic effects on effector T cells, mouse models demonstrate that intrasplenic injection of lymphoma cells also induces expansion of CD4+CD25+ Tregs that is reversible with an IDO inhibitor." (PMID 25941795, 2015).
lymphoma (continued). "For example, T cell immunoglobulin and mucin domain-containing molecule 3 (Tim-3), which can directly induce tolerance in CD4+ T cells and inhibit Th1 polarization needed for an anti-tumor response, was found to be preferentially expressed on lymphoma-derived endothelial cells." (PMID 25941795, 2015). "Defective NK phenotype, in addition to CD4+ depletion and dysfunction, may participate to the increased incidence of lymphoma in HIV patients." (PMID 25908934, 2014). "The median CD4 NADIR was at 157/μl, the median CD4 count at diagnosis of lymphoma at 81/μl." (PMID 25394152, 2014). "Taken together, findings from this large prospective study of survival in HIV-infected patients suggest that maintaining higher CD4+ T-cell counts is a key factor to improve prognosis after both ADCs and NADCs, in particular when considering Kaposi sarcoma and the lymphomas." (PMID 24760049, 2014). "Interestingly CD4 was ≥250 cells/mm3 in three of the four switches to second-line triggered by lymphoma." (PMID 23437399, 2013). "To test whether TGF-β was involved in the differentiation of T cells, we determined the effect of TGF-β on the generation of TH1 (CD4+IFN-γ+), TH17 (CD4+IL-17+) and Treg (CD4+Foxp3+) cells in lymphoma specimens." (PMID 23555036, 2013). "Likewise NOD/SCID mice reconstituted with CD34+ HP/HSCs transduced with a lentivirus vector expressing the Tax protein also developed CD4+ lymphomas." (PMID 22969759, 2012). "Marek’s Disease (MD)—a CD4+ T cell lymphoma of chickens caused by the Gallid herpesvirus type 2 (GaHV-2; MDV)—is a unique natural animal model for herpesvirus induced lymphomagenesis in general and CD30hi lymphomas specifically." (PMID 22979947, 2012). "Our transgenic mice developed a mature T-cell leukemia/lymphoma (CD4+ or CD8+) similar to ATL." (PMID 21483764, 2011). "One example of such a scenario could be lymphomas that develop in HIV-infected patients whose SHR-inducing CD4+ T cells are severely suppressed." (PMID 21179576, 2010). "Additionally, as shown in this pilot study, the peripheral CD4 T cells in HIV-1 patients strikingly resemble the migratory T lymphoma cells in terms of carrying active cofilin." (PMID 18928553, 2008). "EBV-specific CD4+ T cells were assessed 0.5–4.7 y prior to diagnosis of lymphoma." (PMID 17388662, 2007). "Aiming at distinguishing generally depressed CD4+ T cell activity from specifically decreased anti-EBV responses in the participants who developed PCNS lymphoma, we tested the CMV-specific CD4+ T cell-response in CMV-positive cases (n = 4), and compared it to CMV-positive controls (n = 4)." (PMID 17388662, 2007). "However, FC already is a routine diagnostic tool employed to enumerate CD4+ T cells and CD34+ progenitor cells and to screen for HLA-B27 antigen and leukemia/lymphoma immuno-phenotyping." (PMID 16472397, 2006). "CD4+8+ lymphomas recovered after i.t. transfer maintain a CD4+8+ phenotype in long-term culture." (PMID 1840416, 1991). "In both the E.G7-OVA lymphoma model and the Lewis lung carcinoma model, vaccination using an amino-rich FN nanoplatform loaded with tumor antigens and immunostimulatory CpG ODNs greatly enhances the cell populations of typical T lymphocytes in splenocytes such as CD4+ and CD8+ T cells." (PMID 38932378, 2024). "The precise mechanism remains unknown, but it is hypothesized that the interaction between HLA type II-expressing lymphoma cells and CD4+ T cells may contribute to tumor immunity in cALCL, potentially contributing to spontaneous tumor regression and improved outcomes." (PMID 37790936, 2023). "Adoptive transfer of wild-type or TET2-deficient T cells retrovirally transduced to overexpress RhoA-G17V into T-cell deficient murine hosts resulted in CD4+ T cell expansion, disruption of peripheral T cell homeostasis and eventually lethal inflammation but no lymphoma was noted." (PMID 37841428, 2023).